RN7SKP279 (RN7SK pseudogene 279)
Gene: Miscellaneous RNA gene on chromosome 11 (127,407,851 to 127,408,148, forward strand). Ensembl gene ENSG00000223315.
Homologues: Orthologues: chimpanzee 7SK (93% identical). Paralogues in human: RN7SKP180 (74% identical), RN7SKP250 (73% identical), RN7SKP131 (73% identical), RN7SKP217 (73% identical), RN7SKP63 (73% identical), RN7SKP189 (73% identical), RN7SKP78 (73% identical), RN7SKP9 (73% identical), RN7SKP221 (72% identical), 7SK (72% identical), RN7SKP230 (72% identical), RN7SKP176 (71% identical), and 284 more.